NLRP3 (NLR family pyrin domain containing 3)
Diseases named in the same sentence as NLRP3 in open-access papers (continued):
Sharing a sentence is not in itself a finding about the gene and the disease.
Cognitive impairment (continued). "Here, we aimed to investigate the involvement of NLPR3 inflammasome activation in NEC-related enterocolitis and neuroinflammation, especially long-term cognitive impairment, meanwhile, explore the protective effect of NLRP3 inhibitor MCC950 on NEC in mice." (PMID 33676524, 2021). "In conclusion, inhibiting HMGB1 that stops self-reinforcing vicious loop from the NLRP3 inflammasome is a perspective treatment strategy of cognitive impairment after TBI." (PMID 34666797, 2021). "Cognitive impairment in the late stage of traumatic brain injury (TBI) is associated with the NOD-, LRR and pyrin domain-containing protein 3 (NLRP3) inflammasome, which plays an important role in neuroinflammation." (PMID 34666797, 2021). "Another study showed that inhibition of the NLRP3 inflammasome reduced Aβ deposition, neuro-inflammation, and cognitive impairment in an AD mouse model." (PMID 33525754, 2021). "Our previous study found that miR-138-5p plays a vital role in cognitive impairment by targeting NLRP3." (PMID 34599154, 2021). "The neuroinflammation caused by the NOD-, LRR and pyrin domain-containing protein 3 (NLRP3) inflammasome and its role in cognitive impairment are receiving increasing attention." (PMID 34666797, 2021). "Altogether, our present data suggest that the NLRP3 inflammasome plays an important role in cognitive deficits in EAE, possibly via the alteration of astrocyte phenotypes." (PMID 32415059, 2020). "Ac-YVAD-CMK can attenuate anesthesia (isoflurane)-induced activation of NLRP3 inflammasome in aged brain, thus ameliorating cognitive deficits." (PMID 32046097, 2020). "Surgical operation/anesthesia (sevoflurane) increases the activation of NLRP3 inflammasome, leading to cognitive impairment." (PMID 32046097, 2020). "Of the three tested antibiotics, DDS was effective in the molecular regulation of NLRP3 inflammasome activators that are important in mild cognitive impairment (MCI), Parkinson’s disease (PD), and AD." (PMID 32824985, 2020). "Honokiol, a poly phenolic compound, has anti-inflammatory, anti-oxidant, and anti-tumor properties and has shown inhibitory effects on NLRP3 inflammasome and restorative effects on cognitive impairment." (PMID 32046097, 2020). "Our results suggest that the NLRP3/caspase-1 pathway-induced pyroptosis mediates cognitive deficits in a mouse model of SAE." (PMID 30276509, 2019). "There were also interaction effects on cognitive impairment, activation of NLRP3 inflammasome, and the upregulation of IL-1β between hypercapnia treatment and hypoxia treatment." (PMID 29304864, 2018). "This study is carried out to determine the critical role of the NOD-like receptor protein 3 (NLRP3)-caspase-1 pathway in isoflurane-induced cognitive impairment." (PMID 29665808, 2018). "We previously demonstrated that isoflurane GA induced hippocampal NLRP3 inflammasome activation and cognitive deficits in aged mice." (PMID 30524241, 2018). "There were interaction effects on cognitive impairment, apoptosis of hippocampal neurons, activation of NLRP3 inflammasome, and upregulation of IL-1β between hypercapnia treatment and hypoxia treatment." (PMID 29304864, 2018). "NLRP3 inflammasome activation has also been suggested to be the mechanism for the neurotoxicity and cognitive impairment induced by polybrominated diphenyl ethers, materials used widely in industry." (PMID 29665808, 2018). "This is a response to readers' comments on our paper entitled "Critical role of NLRP3-caspase-1 pathway in age-dependent isoflurane-induced microglial inflammatory response and cognitive impairment" published in the Journal of Neuroinflammation this year." (PMID 30217141, 2018). "Conversely, elevated NLRP3 reflects systemic and neuroinflammation, which may exacerbate fatigue, cognitive impairment, and emotional distress, thereby reducing overall quality of life." (PMID 41601525, 2026).
Cognitive impairment (continued). "Ising demonstrated that activation of the NLRP3 inflammasome in microglia accelerates tau pathology and cognitive impairment in an AD mouse model, providing direct evidence that innate immune activation contributes to neurodegeneration through inflammasome signaling." (PMID 41601638, 2026). "Research has shown that repeated propofol administration might lead to long-term cognitive deficits, heightened pro-inflammatory responses, and increased activation of NF-κB and NLRP3 inflammasomes in the brain, leading to cognitive dysfunction." (PMID 39857699, 2025). "Recent evidence has shown a direct correlation between NLRP3 inflammasome activation and cognitive impairments in AD, suggesting that modulating NLRP3 inflammasome activation to reduce pyroptosis may offer new therapeutic targets for AD treatment." (PMID 41249871, 2025). "Notably, severe memory deficits manifest in the later phases of EAE, and cognitive impairments were mitigated by the administration of the NLRP3 inflammasome inhibitor MCC950." (PMID 40050112, 2025). "A. muciniphila may regulate neuroinflammation and cognitive impairment via hippocampal NLRP3‐mediated neuroinflammation, and the peripheral T cell response might modulate the relationship between intestinal microbiota and cognitive behavior." (PMID 40050112, 2025). "Similarly, in a sevoflurane-induced cognitive impairment model in aged mice, reactive oxygen species (ROS) triggered NLRP3 activation, leading to pyroptosis of hippocampal microglia." (PMID 40914484, 2025). "Remarkably, A. muciniphila treatment may exhibit anxiolytic effects and mitigate cognitive impairment by suppressing hippocampal NLRP3‐mediated neuroinflammation." (PMID 40050112, 2025). "Furthermore, A. muciniphila administration partly regulated cognitive impairment and hippocampal NLRP3‐mediated neuroinflammation." (PMID 40050112, 2025). "To investigate the specific mechanisms of cognitive deficits in mice induced by Pg and Pg OMVs, we assessed whether the NLRP3 inflammasome was activated." (PMID 39932228, 2025). "However, multiple studies have demonstrated that mitophagy suppresses inflammation, including NLRP3 inflammasome-mediated pyroptosis in rheumatoid arthritis, aging muscle, and chronic alcohol exposure-induced cognitive impairment." (PMID 40242759, 2025). "NLRP3 was one of the most studied member in this family, and genetic deletion of NLRP3 or its downstream factor caspase-1 in AD mouse model resulted in reduced Aβ deposition, alleviated cognitive impairment, and decreased neuroinflammation." (PMID 40066444, 2025). "Through NLRP3 inflammasome activation, microglia orchestrate neuroinflammatory responses in concert with systemic immune, metabolic, and cellular alterations, contributing to AD’s pathology and cognitive deficits—a rapidly expanding area of research interest." (PMID 41445867, 2025). "This study aimed to explore whether serum amyloid A (SAA) triggers an inflammatory response by activating the NOD-like receptor protein 3 (NLRP3) pathway, resulting in hippocampal neuron apoptosis and cognitive impairments in mice." (PMID 41230093, 2025). "Importantly, other studies have also demonstrated that inhibiting the NLRP3 inflammasome can reduce AD pathology progression and improve cognitive impairments." (PMID 41249871, 2025). "Additionally, a recent study has demonstrated that knockdown of galectin-3 inhibits the NLRP3 inflammasome, thereby mitigating pyroptosis and ameliorating neuronal damage and cognitive deficits post-TBI." (PMID 41369366, 2025). "NLRP3 inflammasome activation and dysregulation are also considered to be an important process in neuroinflammation, which contributes to the pathogenesis of a variety of cognitive disorders such as AD, PD, and Huntington's disease (HD)." (PMID 38664193, 2024).
Cognitive impairment (continued). "Caspase-1 activation and proinflammatory cytokine release preceded the alteration of AD pathology and cognitive impairment, which might suggest that NLRP3 activation occurred in the early stage of AD." (PMID 39109268, 2024). "Hypercapnia-induced IL-1β overproduction via activating the NLRP3 inflammasome by hypoxia-activated microglia may augment neuroinflammation, increase neuronal cell death, and contribute to the pathogenesis of cognitive impairments." (PMID 39347154, 2024). "Consistent with the findings in cell and in tube experiments, in animal experiments, TauS262E overexpression resulted in increased NLRP3 acetylation and inflammasome activation, leading to the activation phenotype of microglia and neuroinflammation; as well as significant cognitive impairment." (PMID 38488468, 2024). "In addition, a single clinically relevant dose of ketamine (7 mg/kg) can induce an inflammatory reaction and cognitive impairment in the hippocampus of developing rats, which is related to activation of the NLRP3 inflammatory body/caspase-1 axis." (PMID 37962460, 2024). "Evodia lepta extract could significantly protect against cognitive impairment by inhibiting NLRP3 inflammasome in scopolamine-treated mice." (PMID 38284892, 2024). "In order to examine the hypothesis that MINO enhances cognitive impairment by inhibiting NLRP3 expression, the combination of nigericin and MINO was administered." (PMID 38329438, 2024). "They revealed that MCC950, an NLRP3 blocker, or VX-765, a caspase-1 blocker, could mitigate pyroptosis, lessen neuropathological damage, and alleviate cognitive deficits." (PMID 39093513, 2024). "The NLRP3 inflammasome complex is considered a possible therapeutic target for preventing various cognitive impairments due to its response to microbial infections and environmental stimuli, and it can activate caspase-1 and promote the maturation of IL-1β and IL-18." (PMID 39203778, 2024). "Additional articles have also demonstrated that P2 × 7R/NLRP3 is a key factor in migraine-related cognitive impairment and may be a potential therapeutic target for alleviating migraine cognitive impairment." (PMID 38573415, 2024). "Evodia lepta extract could protect against cognitive impairment by inhibiting NLRP3 inflammasome in scopolamine-treated mice." (PMID 38284892, 2024). "Overall, our results suggest that mitophagy may play a vital role in NLRP3 inflammasome activation-mediated cognitive impairment after anesthesia and surgery in aged mice." (PMID 38145993, 2024). "In addition, there have been few animal and clinical studies testing the use of NLRP3 as a therapeutic target for the treatment of cognitive impairment, and the safety and efficacy of such therapeutic strategies need to be evaluated in future." (PMID 37915104, 2023). "Furthermore, abnormal activation of the NLRP3 inflammasome is common in patients with cognitive impairment." (PMID 37915104, 2023). "Additionally, an in vivo study showed that the protective effect of JNK‐IN‐8 on cognitive impairment was blocked by nigericin, an NLRP3 activator." (PMID 36987783, 2023). "Importantly, recent research shows that the expression of NLRP3 in the hippocampus of a cognitive impairment model is upregulated, and the impaired function can be reversed by inhibiting the expression of NLRP3." (PMID 36934348, 2023). "We speculate that probiotics therapy might effectively reconstruct the balance of the intestinal microbiome, which could somewhat inhibit the NLRP3/caspase-1 pathway, thus suppressing inflammatory responses and ameliorating cognitive impairment." (PMID 37179548, 2023). "Given the importance of the NLRP3 inflammasomes in neuroinflammation, these observations suggested that mitophagy activation might attenuate sevoflurane-induced cognitive impairment by inhibiting the NLRP3 inflammasomes." (PMID 36709248, 2023).
Cognitive impairment (continued). "We found cognitive deficits; increased NLRP3 inflammasome in the plasma, ileum, and dorsal hippocampus; decreased ileum and dorsal hippocampal cytokine activation and tight junction proteins; and microbiota composition alterations in the ADMA-infusion young male rats." (PMID 37375772, 2023). "Inhibition of miR-129 by miR-129 antagomir could attenuate NLRP3/caspase-1 mediated pyroptosis and improve cognitive impairment by activating IGF-1/GSK3β signaling pathway via directly targeting IGF-1." (PMID 37332874, 2023). "Simultaneously, we investigated whether NLRP3 inflammasome inactivation by CY-09 could reduce AD classical pathology and oxidative stress and improve cognitive deficits." (PMID 36978970, 2023). "Both in vivo and in vitro experiments showed that isoflurane could activate the NLRP3/caspase‐1 pathway and upregulate the secretion of IL‐18 and IL‐1β, and accelerate cognitive impairment." (PMID 38680509, 2023). "The first aim of this study was to examine whether the NLRP3 inflammasome plays an important role in cognitive impairment in young male rats with increased circulating ADMA, and the potential neuroprotective effects of resveratrol." (PMID 37375772, 2023). "Previous studies have shown that NLRP3 inflammasome could drive tau pathology and aggravate cognitive impairment." (PMID 37312196, 2023). "NLRP3 inflammasome is activated in AD and mild cognitive impairment (MCI) brains and APP/PS1 mice." (PMID 36918872, 2023). "In addition, microRNA-138-5p has been reported to regulate hippocampal neuroinflammation and cognitive impairment in rats through the NLRP3 signaling pathway." (PMID 36934348, 2023). "The mitochondrial protectant dexpramipexole (DPX) could sustain mitochondrial function and inhibit NLRP3/caspase-1 pyroptosis pathway, thus ameliorating neuroinflammation and cognitive impairment in SAE." (PMID 37332874, 2023). "EA ameliorates cognitive impairment by inhibiting NLRP3 inflammasome activation in stroke rats." (PMID 36925735, 2023). "Finally, we describe NLRP3 inflammasome antagonists as targeted therapies to improve cognitive impairment." (PMID 37915104, 2023). "NLRP3 inflammasome activation has been reported to be involved with cognitive deficits." (PMID 37179548, 2023). "The activation of NLRP3 inflammasomes enhances AD progression by mediating chronic inflammatory responses, which are partly involved in restricting glial function, and mediating synaptic dysfunction and cognitive impairment, as well as BBB dysfunction." (PMID 36770920, 2023). "Our findings suggest that anesthesia and surgical procedures trigger neuroinflammation and cognitive deficits, which may be due to NLRP3–GABA activation in the hippocampus of aged mice." (PMID 37434240, 2023). "Similar to previous research results, our results show that Hsp22 overexpression pretreatment can inhibit the expression of NLRP3, Caspase-1, IL-1β and proinflammatory cytokines in hippocampal neurons, improve cognitive impairment in mice, and improve learning and memory capabilities." (PMID 36934348, 2023). "Notably, recent research has shown promising results, demonstrating that specific NLRP3 inhibitors attenuated the NLRP3 inflammasome activity in vivo, reduced tau and Aβ levels, and diminished cognitive impairment." (PMID 37793010, 2023). "In addition, we confirmed that Dex administration exerts neuroprotective effects and improves cognitive impairment by directly regulating NLRP3 inflammasome activation in an in vitro POCD model." (PMID 35955939, 2022). "In addition, Pseudoginsenoside-F11 present in American ginseng restored cognitive impairment in APP/PS1 mice by regulating the Nrf2/ARE/NLRP3 pathway." (PMID 35418995, 2022). "Moreover, several studies have proven that inhibition of the NLRP3 inflammasome reduced tau aggregation and decreased the amyloid burden, which in turn diminished cognitive impairment in AD mice." (PMID 36012243, 2022).
Cognitive impairment (continued). "Furthermore, MCC950 also dampens NLRP3 activation and cognitive impairment triggered by isoflurane in mice." (PMID 35858988, 2022). "Overexpressing HSPB8 in the hippocampi could inhibit NLRP3 inflammasome activation via regulation of Drp1 phosphorylation (p-Drp1S616), reduce oxidative stress, and relieve cognitive impairments in diabetic mice." (PMID 35958024, 2022). "Furthermore, quercetin ameliorates cognitive impairment in aging mice by inhibiting NLRP3 inflammasome activation." (PMID 35646138, 2022). "Activation of NLRP3 could induce inflammation and improve the cognitive impairment during normal aging and neuropathological processes." (PMID 36352898, 2022). "Consequently, surgery-induced POCD mice showed cognitive impairment and an elevated inflammatory response with increased NLRP3 inflammasome activation." (PMID 35955939, 2022). "In conclusion, inhibition of NLRP3 can potentially improve cognitive impairment in SAE." (PMID 35958583, 2022). "Moreover, oligodendrocyte glycolytic deficiency through the dynamin-related protein 1- hexokinase 1- NLR family pyrin domain containing 3 signaling axis contributes to white matter degeneration and cognitive impairment in AD." (PMID 36353631, 2022). "The present study demonstrated that idebenone improves neuroprotection and rescues cognitive deficits induced by sustained immune stimulation, LPS-mediated neurogliosis, NLRP3 inflammasome activation and subsequent inflammatory responses in male and female WT mice." (PMID 35222363, 2022). "Specific inhibitors of NLRP3 that exhibit various mechanisms to attenuate the activity of NLRP3 have been tested in in vivo studies and have yielded promising results, as shown by the reduced level of tau and Aβ aggregates and diminished cognitive impairment." (PMID 36012243, 2022). "Therefore, we examined if the NLRP3 inflammasome contributes to glymphatic dysfunction and cognitive impairment in an aging mouse model of IBD." (PMID 34229722, 2021). "Very recently, it was shown that Chikusetsu saponin IVa may alleviate SEVO-induced neuroinflammation and cognitive impairment by blocking NLRP3, likely through reducing apoptosis of neuronal cells." (PMID 34924922, 2021). "Our study demonstrated that Tuina treatment significantly attenuated cognitive impairment in a rat model of cerebral palsy, which may be mediated by inhibiting NLRP3-mediated pyroptosis in the hippocampus." (PMID 34691200, 2021). "Activation of the NLRP3 inflammasome plays a role in the gastrodin-induced amelioration of cognitive impairment in diabetic rats, and NLRP3 inflammation, a molecular marker involved in inflammatory response, is known to play a key role in the development of cognitive impairment." (PMID 34836549, 2021). "Administration of NLRP3 or caspase-1 inhibitors resulted in a significant increase of microglia ability to clear Aβ deposits, as well as in reduced Aβ deposition and improvement in cognitive impairment and hyperactive behavior." (PMID 34070553, 2021). "Some studies have indicated that NLRP3 inflammasome activation is involved in mediating synaptic dysfunction, cognitive impairment, and microglial dysfunction in AD models, and that the inhibition of the NLRP3 inflammasome attenuates spatial memory impairment and enhances Aβ clearance in AD models." (PMID 32415059, 2020). "We found that NLRP3/ASC deficient mice showed the same degree of cognitive impairment as WT intact mice, and there was no additive protective effect after EP administration." (PMID 32517686, 2020). "In summary, our data show that the NLRP3 inflammasome is activated and contributes to cognitive deficits in EAE mice, and it may act via regulating astrocyte phenotype alteration." (PMID 32415059, 2020). "Thus, we further investigated the role of NLRP3/caspase-1-mediated pyroptosis in cognitive deficit of SAE mice." (PMID 30276509, 2019). "NLRP3 gene deletion had protective effects on cognitive impairment in APP/PS1 transgenic mice." (PMID 31461911, 2019).